IL6 (interleukin 6)
Diseases named in the same sentence as IL6 in open-access papers (continued):
Sharing a sentence is not in itself a finding about the gene and the disease.
lung carcinoma (continued). "In addition, the use of serum interleukin-1β (IL-1β), interleukin-6 (IL-6), and interleukin-8 (IL-8) in combination with carcinoembryonic antigen (CEA) as a biomarker panel for the detection and prediction of lung cancer metastasis are being studied." (PMID 36874133, 2023). "While this finding is concordant with research on IL-6 and CRP in lung cancer patients undergoing chemotherapy and in prostate cancer patients treated with androgen deprivation therapy, it is in contrast to research examining cytokines and fatigue in other cancer patient populations." (PMID 37444517, 2023). "An interesting observation was that several of the proteins most strongly associated with lung cancer, including CEACAM5, IL6, and SCF, did not have any stable connections with the identified markers." (PMID 37264016, 2023). "IL-6 plays the role as an activator of JAK and STAT 3 as well as inducing lung cancer metastasis." (PMID 36986550, 2023). "In addition to IL6, the promoting effect of CAFs on EMT programming in lung cancer cells is also mediated by the secretion of CXCL12 and high mobility group box 1 (HMGB1), which activate the CXCR4/β-catenin/PPARδ and NFκB signaling pathways, respectively." (PMID 38139154, 2023). "In addition, we clarify that Q11 can inhibit the activation of the IL‐6/STAT3 pathway and the MAPK/ERK pathway, suggesting that Q11 regulates specific signaling pathways critical for inflammatory responses in lung cancer." (PMID 37875398, 2023). "Comparing the high C3 group to the low C3 group in lung cancer patients, we found that the levels of serum CRP (82.37 (61.89, 90.91) vs. 51.90 (43.19, 60.21), p < 0.05) and IL-6 (89.80 (66.57, 127.13) vs. 53.69 (31.61, 57.68), p < 0.05) were significantly higher in the high C3 patients." (PMID 36769748, 2023). "In a study in which the levels of IL-6 and IL-1βin the serum were measured, it was shown that patients with lung cancer had higher levels of IL-6, regardless of race." (PMID 37373987, 2023). "Other potentially important cytokines, such as TGF-b1, that were shown to have an important correlation with IL-6 in lung cancer diagnosis were not included in this study due to limited funds and cost-effectiveness considerations." (PMID 37373987, 2023). "Cancer cell-derived IL-6 acted to promote tumorigenesis in BCA, HCC, and lung cancer." (PMID 37480115, 2023). "We found that propionate inhibited TLR2- and TLR3-induced lung cancer migration, invasion, and colony formation accompanied by the inhibition of the cAMP-AMPK-TAK1 signaling axis for the activation of NF-κB and the production of CCL2, IL-6, and MMP2 cytokines." (PMID 37287005, 2023). "Other studies have also shown that the treatment of lung cancer cell lines with IL-6 alone did not induce EMT, although the presence of receptor components was not confirmed." (PMID 36828915, 2023). "Our studies also suggested the inhibition of IL-6/JAK2/STAT3 signal transduction by the exogenous rhTβ4 maybe part of reason for its inhibitory effect on IPF and lung cancer." (PMID 36835236, 2023). "High baseline levels of CRP and IL-6 trended toward shorter median time to lung cancer diagnosis, suggesting that IL-1β-inducible CRP and IL-6, similar to ctDNA at baseline, correlate positively with a more rapid progression to lung cancer diagnosis." (PMID 36074553, 2022). "In addition, IL-6 can induce macrophage infiltration in NSCLC, which in turn promtes cancer cell invasion and angiogenesis in lung cancer." (PMID 36520870, 2022). "The IL-6/STAT3 pathway is hyperactivated in patients with many cancer types, including lung cancer." (PMID 36547079, 2022).
lung carcinoma (continued). "At the same time, lung cancer cells often downregulate STAT3 inhibitor SOCS3 which exacerbates the IL-6/STAT3 loop; overexpression of SOCS3 and PIAS can restore normal tumor suppression ability." (PMID 35406557, 2022). "Furthermore, the result showed that the expression level of GPX8 was positively correlated with IL6 and CCL2 in lung cancer." (PMID 35978854, 2022). "Knockdown of GPX8 obviously inhibited LUAD metastasis through the modulation of focal adhesion pathway and GPX8‐mediated IL6 and CCL2 production of CAF may play crucial role for lung cancer metastasis." (PMID 35978854, 2022). "Besides, CAF‐secreted IL‐6 induces drug resistance by promoting EMT and acquiring stemness of lung cancer cells." (PMID 35603909, 2022). "A study on the natural compound polyphyllin I pointed out that the regulation of IL‐6/STAT3 signalling EGFR‐TKI may reverse epithelial‐to‐mesenchymal transition and serve as a potential new way to overcome the EGFR‐TKI resistance in lung cancer." (PMID 35605028, 2022). "In cytokine analysis during immunotherapy, we observed a negative correlation between IL-6 concentration and clinical benefit in lung cancer patients after the third cycle of immunotherapy." (PMID 36091125, 2022). "In conclusion, the present study screened 46 DEMs in GSE17681 and 1029 DEGs in GSE18842 and identified six hub genes related to lung cancer, including mTOR, NF1, CHD7, ETS1, IL-6, and COL1A1, which might be potential targets for lung cancer." (PMID 36211008, 2022). "We aim to describe the characteristics of hepcidin, IL-6, and TNF-α levels in anaemia of lung cancer patients with operative tumour as well as to investigate the potential diagnostic capabilities of hepcidin in combination with IL-6, TNF-α, and acute phase proteins." (PMID 36612220, 2022). "IL-6 induces DNA repair in CD133+ CSC-like cells in response to the radiation treatment of lung cancers and promotes stemness during the cisplatin resistance in lung cancer cells." (PMID 36550571, 2022). "The present study identified six hub genes that were related to lung cancer, including mTOR, NF1, CHD7, ETS1, IL-6, and COL1A1, which might be a potential target for lung cancer." (PMID 36211008, 2022). "The IL-6/STAT3 pathway plays an important role in tumor metastasis, including lung cancer." (PMID 36547079, 2022). "In addition, six hub genes that were related to lung cancer were identified as hub genes, including mTOR, NF1, CHD7, ETS1, IL-6, and COL1A1." (PMID 36211008, 2022). "In this study, the GSP + IR group significantly inhibited IL-6 levels and increased IFN-γ levels 12 hours after irradiation in lung cancer-bearing mice, suggesting that GSP played a role in mitigating inflammation and suppressing lung cancer." (PMID 33854585, 2021). "Using lung cancer models, others have shown that miR-21 alters the tumor microenvironment by increasing the secretion of the pro-inflammatory cytokines TNF- α and IL-6, through the activation of NF-κB, which decreases the number of CD8+ TIL and promotes the polarization of M2 macrophages." (PMID 33672628, 2021). "The BCG+ KLN205 (KLN205 cancer cell injection after BCG treatment) NOX4 KO mice group showed reduced tuberculous fibrosis-promoted metastatic potential of lung cancer, increased autophagy, and decreased expression of TGF-β, IL-6, and TNF-α compared to the BCG+KLN205 WT mice group." (PMID 33567693, 2021). "The Rab37/IL-6/STAT3/PD-1 axis in immune cell models prompted us to determine whether concurrent blockade of IL-6 and CTLA-4 in vivo would provide a rational treatment to circumvent current PD-1-targeted immune-modulatory therapy for lung cancer." (PMID 34093869, 2021).
lung carcinoma (continued). "Western blot analyses revealed that the protein expression of AKT1, IL6, VEGFA, MMP9 in lung tissue of COPD and lung cancer was significantly increased in the model group and hesperetin could dose-dependently prevent these protein expressions (P < 0.01)." (PMID 34262419, 2021). "Likewise, lung cancer cells activate macrophages via TLR2/6 and 9 to produce TNF-α and IL-6 resulting in a rapid metastatic progress." (PMID 34476575, 2021). "Because EML4-ALK interacted with the JAK2-STAT pathway resulting in the phosphorylation of STAT proteins in EML4-ALK-positive lung cancer cells, we investigated whether IL4 or IL6 activated the JAK2-STAT pathway in these cells." (PMID 34090412, 2021). "The graph displaying the distribution of IL-6 concentrations among groups indicates a peak in IL-6 concentrations in patients with stage IIB (me = 44.14 pg/mL), IIIA (me = 47.36 pg/mL), and IIIB (me = 37.00 pg/mL) lung cancer." (PMID 34439874, 2021). "Collectively, these data reveal that miR-708 is suppressing IL-6 production independent of AA signaling in lung cancer cells." (PMID 33776573, 2021). "The most known cytokines to induce T cell dysfunction are IL-10, IL-6 and TNF-α, while TGF-β role in cancer is mostly related to epithelial-to-mesenchymal transition (EMT), invasion and metastasis in melanoma, breast and lung cancer." (PMID 33466674, 2021). "Interestingly, both curcumin and metformin, an anti-diabetic drug, were found to inhibit EMT by blocking the IL-6/STAT3 axis–curcumin in hepatocellular carcinoma and metformin in lung cancer." (PMID 34944855, 2021). "Related to this, it was very recently reported that CRP and IL-6 levels were significantly higher among 10,061 atherosclerosis patients subsequently diagnosed with lung cancer than among those not subsequently diagnosed with lung cancer." (PMID 33173057, 2020). "Observation on IL-6 expressions displayed that the IL-6 was sporadically distributed in a few renal tubules in cortex and medulla in kidney in the sham mice, and relatively higher in the renal tubules in cortex in 1 × 106 LLC1 cell-implanted lung cancer mice." (PMID 33260558, 2020). "In addition to M-CSF, among the inflammatory factors analyzed in our study, MCP-1 and IL-6 were increased, whereas eotaxin-2 and ICAM-1 were decreased in lung cancer cells overexpressing Oct4." (PMID 32487125, 2020). "NF‐κB inhibitor significantly reduced the EMT ability, migratory and invasive capacities of lung cancer, as well as the elevated expression of TIM‐4 induced by IL‐6 stimulation, supporting the point that IL‐6 promoted metastasis of lung cancer by up‐regulating TIM‐4 via NF‐κB." (PMID 32020709, 2020). "Furthermore, we confirmed that overexpressing p65 elevated IL6 expression, and subsequent STAT3 activation resulting in enhanced lung cancer cell growth rate." (PMID 32963220, 2020). "Soluble factors such as IL‐6 and IL‐8, whose expression notably increases upon leukaemia–CP fibroblast interaction, have been recently described as responsible for CAF‐induced chemoresistance in breast and lung cancer cells." (PMID 32686161, 2020).
lung carcinoma (continued). "TAMs also stimulate the expression of IL-1, IL-6, and IL-8 in lung cancer cells through TLR signaling, serving to maintain the inflammatory microenvironment of the tumor and promote the development and progression of lung cancer." (PMID 33224886, 2020). "TNF, EGFR, MYC, IL-6, and JUN were identified as major hub genes of HCT on lung cancer." (PMID 32595734, 2020). "For example, meroterpenoids, isolated from the brown seaweed Cystoseira usneoides, significantly reduced the production of TNF-α, IL-6, and IL-1β, suppressed COX-2 expression, and displayed higher cytotoxic activities against lung cancer cells compared with normal lung cells." (PMID 33537234, 2020). "Consistent with the report, we found that IL‐6 promoted migration and EMT of lung cancer cells." (PMID 32020709, 2020). "KL inhibits lung cancer cell proliferation, growth, invasiveness, and migration and fosters apoptosis, effects, at least in part, dependent on IGF-1R/AKT and Wnt3a/β-catenin signaling and on reduced interleukin 6 (IL-6) and IL-8 production." (PMID 33520985, 2020). "In non-small cell lung carcinoma, CRP, IL-6, and interleukin 8 (IL-8) serum levels were increased in cachectic compared to non-cachectic lung cancer patients." (PMID 33329046, 2020). "Since IL6 could promote STAT3 signaling pathway, we further evaluated IL6 expression after knocking down FAS in lung cancer cells." (PMID 32963220, 2020). "We observed higher IL-6 levels in the lung cancer tissues of smokers than in those of subjects who had never smoked." (PMID 31367260, 2019). "Furthermore, IL-6 inhibition dramatically suppressed MMP2/9 and vimentin expression but elevated E-cadherin expression all four lung cancer cell lines treated with aADSCs-CM." (PMID 31196220, 2019). "We further treated lung cancer cells with IL-6 (10 ng/ml) in the presence of CDK1i or not, and found CDK1i downregulated GP130 and blocked STAT3 phosphorylation as well." (PMID 30931929, 2019). "Because LDOC1 is a regulator of the IL-6/JAK2/STAT3 axis, LDOC1 may play different roles during different stages of lung cancer." (PMID 30634502, 2019). "Notably, the predominant role of ADAM17 in mediating the pathological consequences of deregulated sIL-6R-driven IL-6 trans-signaling has recently been reported in Kras mutant LAC and cigarette smoke carcinogen (NNK)-induced lung cancer." (PMID 31438559, 2019). "As an important cytokine, IL-6 has been observed to regulate EMT in cancers; therefore, we performed western blotting to detect MMP2/9, E-cadherin and vimentin expression in lung cancer cells treated with ADSC-CM or aADSC-CM." (PMID 31196220, 2019). "Taken together, these findings suggest flavonoid compounds may well be responsible for MH-mediated inhibition of the IL-6/STAT3 signaling pathway in human breast and lung cancer cells." (PMID 31491838, 2019). "In line with this altered gut barrier function, LBP and IL-6 levels were increased in cancer cachectic patients versus cancer non-cachectic patients in two populations of patients (lung cancer and colorectal cancer)." (PMID 29719601, 2018). "USP17 could be induced by cytokines secreted from macrophages because various cytokines, including TNF-α, IL-1β, IL-4, IL-6, IL-8, IL-10, CXCL12, CCL18, and CCL22, were able to induce USP17 expression in H1299 and D121 lung cancer cells." (PMID 30038267, 2018). "A distinct study in EGFR mutant lung cancer cell lines demonstrated that EGFR-specific TKIs engage a positive feedback loop involving induction of FGFRs and IL6, leading to STAT3 activation to promote cell survival and limit overall drug-induced growth inhibition." (PMID 29458371, 2018). "To evaluate the translational value of our findings, we measured serum LBP and IL-6 levels in a cohort of 152 patients suffering from colorectal or lung cancer accompanied or not by cachexia." (PMID 29719601, 2018).
lung carcinoma (continued). "The ability of IL-6 to inhibit tumor cell growth has been suggested, as IL-6 functions synchronously with IL-1 and TNF-α in order to support anti-tumor immunity and has been shown to regulate the ability of AMs in lung cancer to be stimulated by IFN-γ and LPS." (PMID 30365491, 2018). "Adding the physiological dose of IL-6 to the media of USP24-knockdown cells can rescue the effect of USP24 knockdown, suggesting that the USP24-mediated IL-6 in M2 macrophages and in lung cancer is an important factor that affects USP24-induced lung cancer malignancy." (PMID 30266897, 2018). "We are not aware of any published report of upregulation of IL-6 by B(a)P although previously B(a)P has been shown to increase the production of pro-inflammation IL-8 via NFκB activation in lung cancer A549 cell line." (PMID 30155724, 2018). "The IL-6 antibody (siltuximab, CNTO 328) and IL-6 receptor antibody (tocilizumab) belong to a class of therapeutics clinically approved for patients with malignant cancers, including prostate, ovarian, and lung cancers." (PMID 30134951, 2018). "Although this analysis is based on circulating levels of biomarkers and therefore the origin of the signal is not established, IL-6 has been shown to be secreted by tumor infiltrating immune cells and tumor epithelial cells in lung cancer." (PMID 28402963, 2017). "We have recently shown that gefitinib or osimertinib treatment results in the activation of not only STAT3, but also Src-YAP1 signaling, potentially operating downstream of IL-6, to promote cell survival and limit the initial response to EGFR TKI treatment in EGFR mutant lung cancer." (PMID 28521301, 2017). "Additionally, the inhibition of IL-6/STAT3 signaling pathway by IL-6 neutralizing antibody or specific inhibitors of JAK2/STAT3 reversed CAF-CM induced EMT and migration of lung cancer cells." (PMID 29100297, 2017). "Moreover, synergism between IL-6/JAK/STAT3 and TGF-β/Smad signaling, as well as TGF-β and Raf/MAPK, is required to induce EMT in lung carcinomas, suggesting that EMT is orchestrated by several signaling pathways." (PMID 28415568, 2017). "Negative effects of IL-6 signaling in triggering increased tumor growth and drug resistance in lung cancer during cisplatin treatment have been reported." (PMID 28878571, 2017). "In this context it is not surprising that inflammation dependent secretion of IL-6 induces TKI resistance in lung cancer." (PMID 28903416, 2017). "Tocilizumab had a dramatic effect on cancer cachexia induced by IL-6–overexpressing lung cancer and prolonged survival without chemotherapy." (PMID 27068103, 2016). "Activation of Bcl-2 has been reported in prostate CSC studies, but its activation and the regulation by IL-6 signaling in lung cancer CSCs have not been addressed before." (PMID 26675547, 2016). "IL-6, IL-22, and VEGF have also been detected in pleural effusion and lung cancer tissue." (PMID 27445423, 2016). "NF-κB in lung cancer cells is responsible for the induction of several anti-apoptotic and pro-proliferative proteins, as well as inflammatory factors, including Bcl-XL, Bcl-2, PCNA, and IL-6." (PMID 27602766, 2016). "Additionally, NF-κB inhibition resulted in a decreased induction of IL-6, which is an important STAT3 activator that promotes tumor development and growth in colon cancer and lung cancer." (PMID 27602766, 2016). "In sera analyses, IL-6 was detectable in 29 of 75 patients with lung cancer (39%) and not detectable in patients with benign lung diseases." (PMID 26675547, 2016). "All together, these data suggest that ATM could be activated by the treatment with IL-6, hence increases the expression of MMP-3/MMP-13 and promotes lung cancer metastasis." (PMID 26528698, 2015). "Despite IL-6 treatment increased cell retention in the lungs, the inhibition of ATM obviously abrogated IL-6's effect on lung cancer cell retention, indicating that ATM phosphorylation facilitates lung cancer cell metastasis." (PMID 26528698, 2015).